INSL5 (insulin like 5)
Description:
May have a role in gut contractility or in thymic development and regulation. Activates RXFP4 with high potency and appears to be the endogenous ligand for this receptor.
Synonyms: PRO182; UNQ156
Tractability: Antibody: its Gene Ontology location is reachable by antibodies, with high confidence; UniProt places it where antibodies can reach, with medium confidence; UniProt predicts a signal peptide or a membrane-spanning region.
Gene: Protein-coding gene on chromosome 1 (66,797,740 to 66,801,276, reverse strand). Ensembl gene ENSG00000172410.
Subcellular location: Secreted
Pathways (Reactome):
Signal Transduction: G alpha (i) signalling events; Relaxin receptors
Gene Ontology:
Molecular function: protein binding; G protein-coupled receptor binding; hormone activity
Biological process: positive regulation of feeding behavior; signal transduction
Cellular component: extracellular region
Genetic constraint (gnomAD): Loss-of-function variants: 1 observed, 2.45 expected, observed/expected ratio (o/e) 0.41, 90% interval 0.14 to 1.63. That is too few expected variants to judge how well the gene tolerates losing a copy. Missense variants: 152 observed, 156.26 expected, observed/expected ratio (o/e) 0.97, 90% interval 0.85 to 1.11. Synonymous variants: 63 observed, 56.37 expected, observed/expected ratio (o/e) 1.12, 90% interval 0.91 to 1.38.
Homologues: Orthologues: chimpanzee INSL5 (99% identical), macaque INSL5 (96% identical), rabbit INSL5 (64% identical), guinea pig INSL5 (62% identical), mouse Insl5 (58% identical), tropical clawed frog insl5 (27% identical), zebrafish insl5a (22% identical), zebrafish insl5b (21% identical). Paralogues in human: RLN3 (26% identical).
Diseases named in the same sentence as INSL5 in open-access papers:
INSL5 is named in the same sentence as 34 diseases in open-access papers, as found by Europe PMC text mining. Sharing a sentence is not in itself a finding about the gene and the disease. The quoted sentences say what the papers report.
colon cancer (3 papers, 2021 to 2022). "INSL5 was significantly (p < 0.001) downregulated (Log2 fold change = -3.966) in colon cancer and in one of the three colon cancer cohorts." (PMID 35560039, 2022). "INSL5 belongs to the insulin superfamily and is downregulated in colon cancer." (PMID 36293321, 2022).
nasopharyngeal carcinoma (3 papers, 2020 to 2025). A carcinoma arising from the nasopharyngeal epithelium. "INSL5 is a potential diagnostic and prognostic marker as well as a therapeutic target for nasopharyngeal carcinoma (NPC)." (PMID 32657028, 2020). "Based upon previous reports, higher expression of INSL5 promoted nasopharyngeal carcinoma (NPC) progression." (PMID 34419055, 2021).
colorectal cancer (2 papers, 2021 to 2023). A primary or metastatic malignant neoplasm that affects the colon or rectum. "This may be the related regulatory mechanism through which INSL5 affects progression of colorectal cancer, further research may be warranted to understand the precise mechanism." (PMID 34419055, 2021). "We also identified multiple down-regulated genes in colorectal cancer that are supported by recent studies on the gene products of the OTOP2, OTOP3, SPIB, and INSL5 genes." (PMID 37790614, 2023).
Obesity (2 papers, 2023). Accumulation of substantial excess body fat. "In the present study, we evaluated INSL5 plasma levels in a group of patients with obesity before and one year after significant weight and adipose tissue loss obtained by laparoscopic sleeve gastrectomy." (PMID 37297947, 2023). "The present data show that subjects with obesity have INSL5 plasma levels positively correlating with adiposity markers." (PMID 37297947, 2023). "In obese patients, we observed that INSL5 plasma levels showed a strong positive correlation between classic markers of obesity such as BMI, fat mass, and leptin plasma levels." (PMID 37297947, 2023). "The close direct correlation between obesity markers and INSL5 plasma levels, together with the decrease in INSL5 concentration after fat mass reduction, pointed to adipose tissue as a possible source of INSL5." (PMID 37297947, 2023). "Furthermore we investigated the relationship of INSL5 plasma levels with classic obesity related parameters such as BMI, waist circumference, fat mass and with leptin plasma levels." (PMID 37297947, 2023). "Finally, these observations suggest that the modulation of the INSL5/RXFP4 axis might represent a target for the treatment of obesity in humans." (PMID 37297947, 2023).
breast carcinoma (1 paper, 2020). "Rxfp4 was expressed in all three human cancer cell lines, Jurkat, MCF-7 and SupT, while Insl5 was also expressed in the latter two, with both genes showing the highest expression in the breast cancer MCF-7 cells." (PMID 33519716, 2020).
diarrhoea (1 paper, 2026). "In conclusion, this study is the first to explore circulating INSL5 levels in patients with chronic diarrhoea, highlighting a link between INSL5 and rectal bile acids, and revealing that INSL5 concentrations are elevated and associated with diarrhoea severity in BAD." (PMID 40701790, 2026). "Elevated PYY is unlikely itself to be causative of the diarrhoea in BAD and IBS-D, as PYY is known to have anti-secretory and anti-propulsory activity in the colon, contrasting with pro-populsory activity of INSL5 in mice." (PMID 40701790, 2026).
glioma (1 paper, 2020). A benign or malignant brain and spinal cord tumor that arises from glial cells (astrocytes, oligodendrocytes, ependymal cells). "Additionally, the profiles from TCGA database also showed that high INSL5 expression was correlated with poor overall survival in multiple tumors, especially in glioma, kidney renal clear cell carcinoma, sarcoma, uterine carcinosarcoma, and uveal melanoma patients (Fig EV1E–I)." (PMID 32657028, 2020).
hypoglycaemia (1 paper, 2018). "Under fasting conditions, ghrelin and INSL5 levels are elevated to induce hunger and to prevent hypoglycaemia." (PMID 30662430, 2018).
Infertility (1 paper, 2022). "RXFP4 expression in the testes of INSL5-deficient mice resulted in infertility due to irregular length of the oestrous cycle and spermatogenesis disorders." (PMID 36303231, 2022).
inflammatory bowel disease (1 paper, 2020). A spectrum of small and large bowel inflammatory diseases of unknown etiology. "If INSL5 has immunomodulatory effects in the gut-immune axis, it would be expected to play a role in metabolic syndromes, such as inflammatory bowel disease and Crohn’s." (PMID 33519716, 2020).
rectal NETs (1 paper, 2025). "In the context of NEC metabolic biomarkers, INSL5 and its receptor RXFP4 have been identified in colorectal tissues and may play a role in rectal NETs." (PMID 41458541, 2025).
virus infection (1 paper, 2020). "Although INSL5 has been reported to play an important role in glucose homeostasis in mice, there is little knowledge about its roles in virus infection and cancer progression." (PMID 32657028, 2020).
tumor (3 papers, 2018 to 2021). "HCAR3 and INSL5 were expressed in tumor tissue and these were associated with poor survival and warrant further study with regard to their potential utility as CRC therapeutic targets." (PMID 34419055, 2021). "HCAR3 and INSL5 were expressed in tumor tissue and these were associated with poor survival and warrant further studies as potential therapeutic targets." (PMID 34419055, 2021). "INSL5 expression in normal tissue was higher than that in tumor tissue and its high expression was associated with a better prognosis for CRC." (PMID 34419055, 2021). "Mouse studies reported a role for Insl5 in glucose homeostasis and orexigenic signaling, but its function in tumor-associated pathology is unknown." (PMID 29592890, 2018). "Collectively, these data indicated that INSL5 was highly expressed in NPC tumor cell lines and tumor tissues." (PMID 32657028, 2020). "This study reveals that INSL5 promotes tumor progression by regulating cancer cell metabolic reprogramming." (PMID 32657028, 2020). "Abnormally high expression of INSL5 could activate JAK1‐STAT5 signaling to induce aerobic glycolysis to promote NPC tumor growth and invasion dependent on the INSL5 receptor GPCR142." (PMID 32657028, 2020). "Furthermore, INSL5‐overexpressing NPC tumor displayed chemoresistance to conventional chemotherapy, which can be reversed by glycolysis inhibitors 2‐DG or anti‐INSL5/GPCR142 neutralizing antibodies." (PMID 32657028, 2020). "In this work, we found INSL5 was elevated in NPC tumor tissue and the plasma of NPC patients." (PMID 32657028, 2020). "The anti‐INSL5 neutralizing antibody, anti‐GPCR142 neutralizing antibody, and glycolysis inhibitor could be attractive approaches for sensitizing INSL5‐overexpressing NPC tumor cells." (PMID 32657028, 2020). "Additionally, when we combined the treatment of blocking INSL5 or GPCR142 antibodies with conventional chemotherapy (DDP) in tumor‐bearing mice, we found that INSL5 overexpression displayed chemoresistance to DDP treatment, which can be reversed by INSL5 or GPCR142 antibody treatment (Fig EV5E–G)." (PMID 32657028, 2020). "Taken together, our results indicate that the overexpression of INSL5 promoted chemoresistance to conventional chemotherapy, while anti‐INSL5 or GPCR142 neutralizing antibodies could suppress tumor alone or renders NPC cell sensitive to chemotherapy, revealing a novel strategy for NPC therapy." (PMID 32657028, 2020). "Additionally, the acceleration of cell cycle progression and suppression of cell apoptosis by INSL5 may also contribute to NPC tumor progress." (PMID 32657028, 2020). "We then first determine INSL5 protein levels in NPC cell lines, tumor, and plasma samples of NPC patients." (PMID 32657028, 2020). "Consequently, we treated the INSL5‐overexpressing NPC PDX mouse model with anti‐INSL5 and anti‐GPCR142 neutralizing antibodies, and as expected, these treatments markedly inhibited tumor growth." (PMID 32657028, 2020). "In consistent, we found INSL5 expression was mainly detected in cancer cells rather than in stromal cells or normal epithelial cells in 18 NPC tumor samples by immunohistochemistry (Fig EV1D)." (PMID 32657028, 2020).
cancer (2 papers, 2020). A tumor composed of atypical neoplastic, often pleomorphic cells that invade other tissues. "In conclusion, INSL5 enhances NPC progression by regulating cancer cell metabolic reprogramming and is a potential diagnostic and prognostic marker as well as a therapeutic target for NPC." (PMID 32657028, 2020). "Collectively, most of NPC cancer cell lines express high levels of INSL5 despite many of these cell lines have lost EBV after maintaining in vitro for many passages." (PMID 32657028, 2020). "Importantly, inhibition of INSL5 function or its downstream factors by various methods reversed INSL5‐induced cancer progression in vitro and in vivo, suggesting INSL5 is a potential therapeutic target for NPC." (PMID 32657028, 2020). "Overall, these results indicated that the presence of INSL5 enhanced glycolysis in cancer cells." (PMID 32657028, 2020). "The present study uncovered new roles of INSL5 in promoting cancer progression." (PMID 32657028, 2020). "To date, there has been limited study on the function of INSL5 in cancer." (PMID 32657028, 2020). "Mechanistically, INSL5 enhanced phosphorylation and nuclear translocation of STAT5 and promoted glycolytic gene expression, leading to induced glycolysis in cancer cells." (PMID 32657028, 2020). "Collectively, the results show INSL5 promotes NPC progression by enhancing cancer cell proliferation and invasion abilities through an autocrine model of action, which depends on the expression of the INSL5 receptor GPCR142 on cancer cells." (PMID 32657028, 2020). "Mechanistically, we identified that INSL5 enhanced the phosphorylation and nuclear translocation of STAT5 and promoted glycolytic gene expression, which in turn induced metabolic reprogramming in cancer cells." (PMID 32657028, 2020). "Together, we concluded that INSL5 could enhance key glycolytic gene expression with a concomitant increase in metabolic intermediates (Fig EV3F), indicating that INSL5 mediates glycolytic reprogramming in cancer cells." (PMID 32657028, 2020). "The nonlethal effects observed in INSL5 knockout mice (the knockout of INSL5 resulted in only a reduction in sperm motility and an irregular length estrous cycle) indicate that INSL5 may be good target for cancer therapy probably with no lethal effects." (PMID 32657028, 2020).
gastrointestinal disease (1 paper, 2026). A disease that occurs in the gastrointestinal system, excluding the hepatobiliary system. "No studies to date have assessed INSL5 levels in patients with gastrointestinal disease, despite its association with promoting colonic motility in animal studies." (PMID 40701790, 2026).
INSL5 also shares sentences with these, for which no sentence is quoted: Crohn disease (2 papers); polycystic ovarian syndrome (2); cryptorchidism (1); diabetes (1); head and neck cancer (1); Insulin resistance (1); malaria (1); metabolic disorders (1); metabolic syndrome (1); narcolepsy (1); Pituitary Gland Disease (1); rectal neuroendocrine tumor (1); sarcoma (1); T-cell non-Hodgkin lymphoma (1); tenosynovitis (1); type 2 diabetes (1); ulcerative colitis (1); uterine carcinosarcoma (1); uveal melanoma (1).